PLPP3 (phospholipid phosphatase 3)
Diseases named in the same sentence as PLPP3 in open-access papers:
PLPP3 is named in the same sentence as 71 diseases in open-access papers, as found by Europe PMC text mining. Sharing a sentence is not in itself a finding about the gene and the disease. The quoted sentences say what the papers report.
coronary artery disease (14 papers, 2014 to 2024). "Single nucleotide polymorphisms have been identified in PLPP3 (the gene that encodes LPP3) that are associated with an increased risk of coronary artery disease." (PMID 33076403, 2020). "Genome-wide association studies identified PLPP3 as a gene that plays a role in coronary artery disease susceptibility." (PMID 28291223, 2017). "In addition, GWAS have previously associated variants in PLPP3 with several chronic inflammatory diseases, including coronary artery disease and eosinophilic esophagitis." (PMID 34134627, 2021). "In addition, a genetic variant at phospholipid phosphatase 3 (PLPP3) implicated in coronary artery disease and ischemic stroke by genome-wide association studies (GWAS) has been shown to regulate endothelial mechanosensing responses to hemodynamic forces." (PMID 32601597, 2019). "Genome-wide association studies in humans identified single nucleotide polymorphisms in PLPP3 (phospholipid phosphatase 3) as a novel locus associated with risk for coronary heart disease that was independent of traditional risk factors." (PMID 37059333, 2023).
atherosclerosis (11 papers, 2013 to 2025). A disease characterized by the build-up of fatty material and calcium deposition in the arterial wall resulting in partial or complete occlusion of the arterial lumen. "The PLPP3 gene is associated with platelet aggregation in atherosclerosis, a complication common to many SSc patients." (PMID 39350339, 2024). "The main result of the present manuscript is the demonstration that hepatocyte-specific Plpp3 deletion is associated with increased atherosclerosis progression." (PMID 28291223, 2017). "In conclusion, the present work provides the first demonstration of the role of Plpp3/LPP3 in atherosclerosis development in an animal model and further provides experimental evidence supporting clinical observations relating PLPP3 polymorphisms to CAD susceptibility." (PMID 28291223, 2017). "Additionally, plasma lipidomic analysis suggested a molecular basis for the observed results, indicating low-abundant lipid species as potential players in the development of atherosclerosis associated with Plpp3 hepatic deficiency." (PMID 28291223, 2017). "Lipidomic analysis showed that hepatic Plpp3 deletion significantly modified the levels of several plasma lipids involved in atherosclerosis, including lactosylceramides, lysophosphatidic acids, and lysophosphatidylinositols." (PMID 28291223, 2017). "The aim of the study was to investigate the effect of Plpp3 deletion on atherosclerosis development in mice." (PMID 28291223, 2017). "LPE(20:3) was increased in mice developing atherosclerosis due to hepatic Plpp3 deletion." (PMID 40176064, 2025). "In the present study, a possible role of Plpp3 in atherosclerosis development was investigated." (PMID 28291223, 2017). "In conclusion, Plpp3 ablation in mice worsened atherosclerosis development." (PMID 28291223, 2017). "Lipidomic analysis suggested that the hepatic Plpp3 deletion may promote atherosclerosis by increasing plasma levels of several low-abundant pro-atherogenic lipids, thus providing a molecular basis for the observed results." (PMID 28291223, 2017). "Thus, with the aim of elucidating the effects of hepatic Plpp3 deletion on circulating lipid levels, which might affect atherosclerosis development, a lipidomic analysis was conducted on Plpp3f/f apoE−/− Alb-Cre− and Plpp3f/f apoE−/− Alb-Cre+ mouse plasma." (PMID 28291223, 2017). "Additionally, global reduction in Plpp3 expression and SMC-specific inactivation of Plpp3 promotes the development of experimental atherosclerosis in mice." (PMID 35383201, 2022). "In addition, the LPA inactivator, phospholipid phosphatase 3 (PLPP3), is repressed in advanced stages of human atherosclerosis." (PMID 30845751, 2019). "The results indicated that the lack of hepatic Plpp3 expression increased the levels of several pro-atherogenic plasma lipid species and led to accelerated atherosclerosis progression." (PMID 28291223, 2017). "However, in a model of atherosclerosis, myeloid-derived PLPP3 does not increase LPA lesion localization or increase atherosclerosis progression." (PMID 33076403, 2020).
breast carcinoma (11 papers, 2017 to 2025). "Specifically, the reduced expression levels of PLPP1 and PLPP3 had been observed in colon cancer and breast cancer." (PMID 37996944, 2023). "Correlation between mRNA expression of SGPP1 and PLPP3 with relapse-free survival in the different breast cancer intrinsic subtypes." (PMID 34235182, 2021). "Correlation between mRNA expression of SGPP1 and PLPP3 with relapse-free survival (RFS) in the systemically treated in different breast cancer intrinsic subtypes." (PMID 34235182, 2021). "Correlation between mRNA expression of SGPP1 and PLPP3 with relapse-free survival in the breast cancer patients with ER, PR, HER2 and LN status." (PMID 34235182, 2021). "There is a number of scientific research for each of the top 10 mRNA genes, well-documenting their significance and association with cancerogenesis: ADAMTS5, TMEM220, ARHGAP20, MICU3; or precisely with breast cancer: COL10A1, MMP11, CAVIN2 (formerly known as SDPR), PLPP3, MME, and CD300LG." (PMID 40724805, 2025). "In this study, we explore the role of LPP mRNA expression (LPP1 gene name PLPP1 and historically PAPP2A; LPP2 gene name PLPP2, PAPP2C; LPP3 gene name PLPP3, PAPP2B) within the human breast cancer TME via in silico research approaches using three large independent cohorts." (PMID 37190226, 2023).
Stroke (6 papers, 2023 to 2025). Sudden impairment of blood flow to a part of the brain due to occlusion or rupture of an artery to the brain. "Another cluster involving vascular diseases and stroke is linked to phospholipid phosphatase 3 (PLPP3)." (PMID 37749083, 2023). "circSCMH1 promotes vascular repair after stroke through FTO-regulated m6A methylation of phospholipid phosphatase 3 (PLPP3)." (PMID 37815911, 2024). "In our study, circSCMH1 overexpression attenuated Plpp3 deficiency by FTO-mediated m6A methylation, and promoted vascular repair after stroke." (PMID 36717587, 2023). "Together, these results suggest that Plpp3 mRNA may be one of the targets of circSCMH1-mediated vascular repair after stroke by FTO." (PMID 36717587, 2023). "Moreover, circSCMH1 promotes translocation of obesity-associated protein into the endothelial cell nucleus via ubiquitination and subsequently facilitates m6A demethylation of Plpp3 mRNA and upregulates Plpp3 expression, thereby enhancing vascular repair after stroke in mice in vivo and in vitro." (PMID 38515760, 2024).
Obesity (5 papers, 2016 to 2024). Accumulation of substantial excess body fat. "PLPP3, which encodes lipid phosphatase (LPP) 3, was found to regulate the synthesis of adipocyte sphingolipids but did not ameliorate diet-induced obesity in mice with the inactivation of PLPP3 adipocyte targeting." (PMID 39682999, 2024).
breast tumors (4 papers, 2019 to 2023). "The results showed that the protein levels of PLPP3 and SGPP1 were decreased significantly in primary breast tumors as compared to normal breast tissue." (PMID 34235182, 2021).
oral squamous cell carcinoma (4 papers, 2017 to 2022). "We have also shown that the expression of the gene coding for LPPs, particularly LPP3 (PLPP3), is downregulated in the tumor tissues from oral squamous cell carcinoma patients compared to adjacent normal tissues." (PMID 34235182, 2021). "Meanwhile, PLPP3 was downregulated in oral squamous cell carcinoma (OSCC) patients, and PLPP3 expression negatively correlated with TNM stage and tumor volume." (PMID 34917513, 2021). "In addition, it has been demonstrated that PLPP3 was downregulated in approximately 70% of oral squamous cell carcinoma (OSCC) patients, and low expression of PLPP3 positively correlated with TNM stage in OSCC patients." (PMID 28851360, 2017).
glaucoma (3 papers, 2020 to 2024). Increased pressure in the eyeball due to obstruction of the outflow of aqueous humor. "PLPP3 (phospholipid phosphatase 3) showed high centrality metric parameters, and it was found to be significantly overexpressed in the optic nerve of glaucoma patients." (PMID 39458974, 2024). "The enzymes depicted in red are upregulated in glaucoma, for example LPIN2 and PLPP3, whereas the GPAT4 depicted in blue are downregulated." (PMID 32602905, 2020).
lung adenocarcinoma (3 papers, 2022 to 2023). A carcinoma that arises from the lung and is characterized by the presence of malignant glandular epithelial cells. "PLPP3 is mainly associated with calcific aortic valve disease, but researchers have found that low expression of PLPP3 is significantly associated with worse OS in lung adenocarcinoma and nonsmoking non-small cell lung cancer patients." (PMID 36818393, 2023). "Moreover, expression of SGPP1 and PLPP3 was associated with overall survival in lung adenocarcinoma and non-small-cell lung carcinoma (NSCLC) patients, where expression of PLPP3 correlated with tumor-infiltrating immune cells in NSCLC patients." (PMID 35163211, 2022).
lung carcinoma (3 papers, 2017 to 2024). "Conversely, the expression levels of PLPP1, PLPP3 and PLPP7 were decreased to varying degrees compared with those in the ANT, indicating that different members of the PLPP family have oncogenic or tumor-suppressive roles in the development of lung carcinoma." (PMID 28851360, 2017).
cardiac hypertrophy (2 papers, 2018 to 2024). "Following Plpp3 overexpression, both cardiac hypertrophy and fibrosis were heightened in PPC-treated SHR rats." (PMID 39403590, 2024).
colorectal cancer (2 papers, 2016 to 2018). A primary or metastatic malignant neoplasm that affects the colon or rectum. "PLPP3 displays reduced expression in metastasising (versus non-metastasising) sporadic colorectal cancer." (PMID 30566430, 2018).
Hypertension (2 papers, 2021 to 2024). The presence of chronic increased pressure in the systemic arterial system. "Our study highlights lipid metabolic dysfunction in hypertension-related diseases, suggesting Plpp3 as a potential therapeutic target." (PMID 39403590, 2024). "Importantly, overexpression of Plpp3 significantly reversed the protective effects of PPC on hypertension-related cardiac and renal injuries, vascular fibrosis, remodeling, and tension." (PMID 39403590, 2024). "Targeting the NF-κB/Plpp3 pathway may offer a promising therapeutic strategy for treating vascular diseases related to hypertension." (PMID 39403590, 2024). "We also identified 21 DEGs (e.g., Fn1, Cd34, Plpp3, Tns1, Nox4, and Npnt) that may be involved in the development of hypertension." (PMID 34862465, 2021).
renal cell carcinoma (2 papers, 2023 to 2024). "Conversely, elevated levels of PLPP2 have been observed in many cancers, including liver and prostate, breast and renal cell cancer, which was opposite to the expression pattern of PLPP1 and PLPP3." (PMID 37996944, 2023).
renal fibrosis (2 papers, 2017 to 2024). A final common manifestation of a wide variety of chronic kidney diseases characterized by glomerulosclerosis and tubulointerstitial fibrosis. "Moreover, renal fibrosis and injury were significantly exacerbated by Plpp3 overexpression." (PMID 39403590, 2024).
diabetes (1 paper, 2021). "Thus, the lipid regulatory and anti-inflammatory roles of PLPP3 in chronic inflammatory diseases lend further evidence for a metabolic-immune axis in diabetes." (PMID 34134627, 2021).
E. coli infection (1 paper, 2023). "Based on DEGs, WGCNA, and MCODE, key genes associated with E. coli infection were discovered, including CXCL3, HSPA1B, TNF, and PLPP3." (PMID 38066783, 2023).
endothelial dysfunction (1 paper, 2021). In vascular diseases, endothelial dysfunction is a systemic pathological state of the endothelium (the inner lining of blood vessels) and can be broadly defined as an imbalance between vasodilating and vasoconstricting substances produced by (or acting on) the endothelium. "Additionally, we observed a significant 9.70-fold decrease in a peptide from phospholipid phosphatase 3 (PLPP3), a protein otherwise known to be protective against endothelial dysfunction." (PMID 34711247, 2021). "Additionally, a significant decrease in the peptide from phospholipid phosphatase 3 (PLPP3) implied a loss of this protein, which enhances endothelial dysfunction and permeability." (PMID 34711247, 2021).
hyperlipidemia (1 paper, 2022). "Hyperlipidemia was achieved by injecting littermate control WT or Plpp3+/− mice with PCSK9D377Y.AAV to lower LDL receptor expression and feeding the animals Western diet." (PMID 35383201, 2022).
invasive breast carcinoma (1 paper, 2021). A carcinoma that infiltrates the breast parenchyma. "Both of the S1P-catabolizing genes, SGPP1 and PLPP3, showed high predictive value for response to systematic therapy in invasive breast carcinoma patients and especially in the HER2+ and basal subtypes." (PMID 34235182, 2021). "Notably, the promoter of PLPP3 was hypermethylated in the primary tumors from invasive breast carcinoma." (PMID 34235182, 2021).
mastitis (1 paper, 2023). Inflammation of breast tissue during lactation or postpartum due to an obstructed duct or infection. "The PLPP3 gene has also been reported to be associated with resistance to clinical mastitis in Holstein cattle." (PMID 36899300, 2023).
parkinsonism (1 paper, 2016). Characteristic neurologic anomaly resulting from degeneration of dopamine-generating cells in the substantia nigra, a region of the midbrain, characterized clinically by shaking, rigidity, slowness of movement and difficulty with walking and gait. "Here we investigated whether the motor deficit of PLPP3-deficient mice may be related to parkinsonism." (PMID 27063549, 2016).
schizophrenia (1 paper, 2020). A major psychotic disorder characterized by abnormalities in the perception or expression of reality. "Therefore, a higher expression of SGPL1 and PLPP3 in the BA8 of patients with schizophrenia may have stemmed from a lower RIN or associated phenomena." (PMID 32346731, 2020). "In the BA8, the transcript expression level of SGPL1 or PLPP3 was also significantly higher in the schizophrenia group than in the controls." (PMID 32346731, 2020). "This suggests that, rather than by increased SGPL1 expression, an S1P-degrading process augmented by elevated PLPP3 expression may, at least in part, be responsible for the lowered S1P content in the corpus callosum of patients with schizophrenia." (PMID 32346731, 2020). "We further examined the correlation of SGPL1 or PLPP3 expression level with RNA integrity number (RIN), as the RIN in the corpus callosum of patients with schizophrenia differed significantly from that of the controls." (PMID 32346731, 2020). "The expression levels of Sphingosine-1-Phosphate Lyase 1 (SGPL1) and Phospholipid Phosphatase 3 (PLPP3) showed a significantly higher (P = .006) and an elevated trend (P = .09), respectively, in the corpus callosum of patients with schizophrenia compared with controls." (PMID 32346731, 2020).
triple-negative breast carcinoma (1 paper, 2021). An invasive breast carcinoma which is negative for expression of estrogen receptor (ER), progesterone receptor (PR), and human epidermal growth factor receptor 2 (HER2). "Correlation between mRNA expression of SGPP1 and PLPP3 with relapse-free survival (RFS) in Pietenpol subtypes of triple-negative breast cancer (TNBC)." (PMID 34235182, 2021).
Uterine leiomyoma (1 paper, 2026). The presence of a leiomyoma of the uterus. "Uterine leiomyoma cultures repressed genes involved in vascular homeostasis (e.g., PLPP3) and preferentially activated pathways related to smooth muscle excitability and vesicle secretion." (PMID 42099382, 2026).
tumor (28 papers, 2005 to 2025). "The top three downregulated DEGs (Ptn, Plpp3, and Boc) were found to be underexpressed in many tumour types (tumour names in green), with a threshold of|log2FC|> 1 and q < 0.01." (PMID 40182023, 2025). "Expression of PLPP3 was positively correlated with tumor-infiltrating immune cells in non-small-cell lung cancer patients." (PMID 34917513, 2021). "SGPP1 and PLPP3 expression show a strong positive correlation with tumor-infiltrating dendritic cells (DCs), CD4+ and CD8+ T cells, neutrophils, and macrophages in the TNBC subtypes." (PMID 34235182, 2021). "A major function of PLPP3 is dephosphorylation of extracellular lysophosphatidic acid, a phospholipid with growth factor-like activity that stimulates tumour cell migration and invasion." (PMID 30566430, 2018). "We, therefore, conclude that low expression of SGPP1 and PLPP3 may hinder the recruitment of immune cells to the tumor environment, resulting in the blockage of cancer cell clearance and a subsequent poor prognosis." (PMID 34235182, 2021). "We demonstrated herein that the expression of SGPP1, PLPP3, and S1P receptors, particularly S1PR4, positively correlates with tumor-infiltrating DCs in TNBC." (PMID 34235182, 2021). "In summary, we found that low mRNA expression of SGPP1 and PLPP3 correlates with worse prognosis in patients with BC, particularly in those with TNBC, and that high expression of both of these genes may promote the infiltration of immune cells, especially DCs, into the tumor microenvironment." (PMID 34235182, 2021). "PLPP3, PLPP4, and PLPP6 were differentially elevated in some cancers, particularly PLPP4 showed “with” and “without” expression in cancer or tumor tissues (T) compared to the respective adjacent normal tissues (N)." (PMID 34917513, 2021).
cancer (22 papers, 2011 to 2025). A tumor composed of atypical neoplastic, often pleomorphic cells that invade other tissues. "Another important component in the regulation of LPA signaling in cancers is the degradation of LPA by LPP1 and LPP3 (PLPP1 and PLPP3, respectively)." (PMID 32824846, 2020). "In vitro experiments had also shown that knockdown of PLPP2 weakened the growth of anchor-dependent cancer cell lines and reduced cell proliferation by delaying S-phase entry, unlike what was seen with PLPP1 and PLPP3." (PMID 37996944, 2023).
infection (3 papers, 2022 to 2025). The state of being infected such as from the introduction of a foreign agent such as serum, vaccine, antigenic substance or organism. "Nine down-regulated DEGs were commonly downregulated in response to either Aβ pathology or MA10 infection (Vegfa, Atp1a2, Slc6a11, Gja1, Slc6a11, Gpr37l1, Plpp3, Gstm1, Agt)." (PMID 41497643, 2025). "The data indicated that the upregulated expression of lipid metabolism-related genes, such as PLPP3 and ZC3H12A, occurred as early as 5 h post-infection." (PMID 39872814, 2024).
neurological disorders (1 paper, 2025). "This system specifically reduces m6A modification on phospholipid phosphatase 3 (PLPP3) mRNA establishing a mechanistic foundation for developing siRNA-based therapeutic strategies against m6A-related neurological disorders." (PMID 40986143, 2025).
PLPP3 also shares sentences with these, for which no sentence is quoted: ovarian carcinoma (7 papers); colon carcinoma (5); ischemic stroke (5); glioblastoma (4); Insulin resistance (3); melanoma (3); abdominal aortic aneurysm (1); adenocarcinoma (1); alcoholic fatty liver (1); anaplastic glioma (1); aneurysm (1); aortic aneurysm (1); brain injury (1); calcific aortic valve disease (1); cancer of the urinary bladder (1); cardiomyopathy (1); Cardiovascular Disease (1); carotid atherosclerosis (1); cervical cancer (1); cholangiocarcinoma (1); coccidiosis (1); diabetic nephropathy (1); eosinophilic esophagitis (1); erythroleukemia (1); fatty liver disease (1); fungal infection (1); glioma (1); head and neck cancer (1); hemangioma (1); ischemia (1).
A further 12 diseases each share a sentence with PLPP3 in 1 paper.